EZH2 (enhancer of zeste 2 polycomb repressive complex 2 subunit)
Diseases named in the same sentence as EZH2 in open-access papers (continued):
Sharing a sentence is not in itself a finding about the gene and the disease.
breast cancer (continued). "Overall, we show that NIC exposure either through smoking in breast cancer patients or upon direct treatment in vitro and in vivo resulted into an increased EZH2 expression in breast cancer cells." (PMID 29396474, 2018). "Here we report that genetic or pharmacological targeting of the epigenetic modifier Ezh2 dramatically hinders metastatic behaviour in both a mouse model of breast cancer and patient-derived xenografts reflective of the Luminal B subtype." (PMID 29959321, 2018). "Our data show that EZH2 is a phosphorylation substrate of p38 in breast cancer, and that pEZH2(T367) promotes metastasis, at least in part by cytoplasmic localization and interaction with cytoskeletal proteins." (PMID 30022044, 2018). "This directly contrasted with findings from recent studies that have utilized other transgenic mouse models to dissect the role of Ezh2 in breast cancer." (PMID 29959321, 2018). "Here, the authors demonstrate that targeting epigenetic modifier Ezh2 hinders metastatic behaviour in Luminal B breast cancer models, and highlight a mechanism where Ezh2 contributes to metastatic behaviour by repression of FOXC1." (PMID 29959321, 2018). "To confirm the protein-DNA binding we performed CHIP-qPCR by immunoprecipitation with EZH2 in MCF-7 breast cancer cells." (PMID 29940916, 2018). "EZH2 is aberrantly overexpressed in various malignant tumors, such as prostate cancer, breast cancer, and ovarian cancer.EZH2 mediates H3K27me3 and functions as a critical factor in promoting tumor growth and metastasis in many malignant tumor models." (PMID 29556394, 2018). "We recently reported that in aggressive ER- breast cancer, EZH2 complexes with RelA/RelB and binds to the Notch1 promoter to activate transcription independent of its methyltransferase activity." (PMID 30022044, 2018). "In the context of breast cancer, our data indicate that Suz12-deleted organoids, like Ezh2-null basal cells, displayed similarities with signatures of claudin-low breast cancers, which are thought to arise from MaSCs." (PMID 30080881, 2018). "In this study, we demonstrated that NIC-induced increased breast cancer progression is mediated through EZH2 and enhanced EZH2 expression in response to NIC is primarily through Myc upregulation." (PMID 29396474, 2018). "Taken together the data suggest that p38-mediated T367 phosphorylation of EZH2 in ER- breast cancer cells promotes a PRC2-independent interaction with cytoplasmic vinculin, leading to phosphorylation of vinculin at Y100 and localization at focal adhesions." (PMID 30022044, 2018). "An increasing amount of meta-analysis data has shown that the abnormal expression of EZH2 is a prognostic factor for patients with various human cancers such as lung cancer, breast cancer and digestive cancers." (PMID 30542123, 2018). "MLL1, G9a, SUV39H1, JMJD3, and EZH2 expressions are increased in glioblastoma multiforme, breast cancer cell, and human fetal lung epithelial cells under hypoxic microenvironment, respectively." (PMID 29449535, 2018). "In contrast, EZH2 interacted with ER and repressed NF-κB target gene expression by inducing H3K27me3 on their promoters in ER positive luminal like breast cancer cells." (PMID 29864144, 2018). "With respect to breast cancer, Ezh2 levels are observed to be elevated and increased expression has been associated with poor survival." (PMID 29959321, 2018). "The aim of the present study was to investigate the correlation of enhancer of Zeste homolog 2 (EZH2) and SET and MYND domain containing 3 (SMYD3) gene polymorphisms with breast cancer susceptibility and prognosis." (PMID 29089464, 2018). "EZH2 is overexpressed in several cancers, including lymphomas and breast cancer, and overexpression of EZH2 correlates with resistance to cisplatin in ovarian cancer." (PMID 29535829, 2018). "EZH2 rs12670401, EZH2 rs6464926, and clinical staging were independent prognostic factors for breast cancer." (PMID 29089464, 2018).
breast cancer (continued). "Together this suggests that EZH2 expression and chromatin remodeling drives breast cancer progression." (PMID 30306389, 2018). "Here in this study, we showed close association of EZH2 and NIC-induced increased breast cancer progression." (PMID 29396474, 2018). "This observed mutual exclusivity supported the mechanism of EZH2-mediated FOXC1 repression in Luminal B breast cancer." (PMID 29959321, 2018). "For instance, EZH2 activates NF-κB target genes in breast cancer, and in a subpopulation of glioblastoma stem cells, EZH2 methylates STAT3, leading to enhanced STAT3 activation." (PMID 29498629, 2018). "Altogether, these data document that T367 phosphorylation is critical for the metastasis-promoting function of EZH2 in breast cancer." (PMID 30022044, 2018). "EZH2 expression is related to the OS of cancer patients and high EZH2 expression as a prognostic factor shows shorter OS for patients with breast cancer." (PMID 29089464, 2018). "The present study for the first time gives an insight into regulation of estrogen-related receptors by histone methylation specifically through methyltransferase EZH2 in breast cancer." (PMID 29940916, 2018). "In breast cancer, we have reported cytoplasmic EZH2 protein in 16% of invasive ER- breast carcinomas from Ghanaian patients." (PMID 30022044, 2018). "We observed that deletion of Ezh2 in a PyVmT-driven model significantly delayed tumour onset, thus indicating that Ezh2 plays an important role in breast cancer progression." (PMID 29959321, 2018). "Collectively, these data show that T367 phosphorylation is required for EZH2 cytoplasmic localization in breast cancer cells, and reveal that cytoplasmic EZH2 expression is sufficient to promote breast cancer cell migration and invasion." (PMID 30022044, 2018). "Angelman syndrome chromosome region (ANCR) modulates the stability of EZH2, and hence suppresses the invasion and metastasis of breast cancer cells." (PMID 30150556, 2018). "Taken together, these data provide compelling evidence that pharmacological intervention targeting the EZH2-dependent repression of a FOXC1-driven transcriptional program can hinder the metastatic properties of human Luminal B breast cancer." (PMID 29959321, 2018). "Overall, our results identify EZH2 as a functional coregulator for estrogen-related receptors especially ERRα and ERRβ in breast carcinoma." (PMID 29940916, 2018). "NIC treatment on normal breast epithelial cells and breast carcinoma cells resulted in the overexpression of EZH2 as detected by western blot assay." (PMID 29396474, 2018). "Since PARP1 inhibition induces accumulation of DNA damage in BRCA1-deficient cells, we tested if inhibition of EZH2 enhances the effect of the PARP inhibitor olaparib in BRCA1-mutated and BRCA1-reconstituted MDA-MB-436 human breast carcinoma cells." (PMID 29535829, 2018). "Our findings identify EZH2 as a relevant coregulator for estrogen-related receptors in breast carcinoma." (PMID 29940916, 2018). "It is assumed that EZH2 promotes breast cancer progression by transcriptional repression of tumor suppressors and by maintaining cells in a stem cell-like state." (PMID 28241804, 2017). "Overexpression of EZH2 is a marker of advanced and metastatic disease in many solid tumors, including prostate and breast cancer." (PMID 29046366, 2017). "Several studies have shown that EZH2 is aberrantly overexpressed in various malignant tumors, such as prostate cancer, breast cancer, ovarian cancer and others." (PMID 28415635, 2017). "EZH2 overexpression is reported in many malignancies including lymphoma, breast cancer, and prostate cancer." (PMID 28401060, 2017). "CDKN1C (p57) is a direct target of EZH2 and is suppressed by epigenetic mechanisms in breast cancer, ovarian cancer, non-small-cell lung cancer etc.." (PMID 29371934, 2017).
breast cancer (continued). "We thought that EZH2 promotes breast cancer progression by transcriptional repression of tumor suppressors; consequently, Ki-67 expression increased in breast cancer cells with high EZH2 expression." (PMID 28241804, 2017). "High EZH2 levels have been observed in cancer stem cell (CSC) populations isolated from primary breast cancer cells compared to normal breast cell lines." (PMID 28410242, 2017). "Further study revealed that in TN breast cancer, EZH2 directly binds to the NOTCH1 promoter to active NOTCH1 signaling, independent of PRC2-mediated H3K27me3." (PMID 28415635, 2017). "It has been reported that EZH2 is transcriptionally induced by estradiol in ERα-positive breast cancer cell lines." (PMID 28418882, 2017). "EZH2 levels have been demonstrated to be increased in CSCs in various malignant tumors, such as melanoma cancer, breast cancer, ovarian cancer, pancreatic cancer, skin cancer, colorectal cancer and leukemia." (PMID 28415635, 2017). "EZH2 was demonstrated to be oncogenic in esophageal cancer, lung cancer, and breast cancer, among others." (PMID 28694563, 2017). "Other investigators have reported that EZH2 promotes neoplastic progression in the breast, and that downregulation in EZH2 expression reduces in vivo tumor growth of breast cancer cells." (PMID 28241804, 2017). "Specifically, they found that ANCR facilitates breast cancer progression and metastasis mainly by decreasing EZH2 stability." (PMID 29137343, 2017). "Next, we examined the association between the percentage of cells positive for EZH2 in the normal TDLU epithelium and subsequent risk of breast cancer in the NHS and NHS II cohorts." (PMID 28253895, 2017). "Conversely, low protein intake is highly effective in inhibiting tumor growth in human xenograft prostate and breast cancer models by reducing expression of EZH2 and histone mark H3-K27me3." (PMID 28758948, 2017). "Further, EZH2 physically bridged the estrogen receptor (ER) and components of Wnt signaling to induce the gene expression in breast cancer cells." (PMID 28410242, 2017). "Specifically, miR-138 overexpression inhibits EMT process by targeting Vimentin and EZH2, thus reducing breast cancer invasion." (PMID 28606130, 2017). "To initially examine the impact of combined inhibition of HOTAIR and EZH2, we treated ovarian and breast cancer cells with HOTAIR siRNA plus EZH2 catalytic activity inhibitor (GSK126), observing increased chemotherapy sensitivity and reduced cell survival." (PMID 28420874, 2017). "Both HOTAIR and EZH2 showed a higher expression level in primary breast cancer samples than metastases." (PMID 29469819, 2017). "Overexpression of EZH2 has been reported in many malignancies such as breast cancer and B Cell Lymphomas." (PMID 29100322, 2017). "EZH2 gene silencing has also been reported to result in a significant reduction in tumor growth in the MB-231 TNBC orthotopic mouse model of breast carcinomas." (PMID 28241804, 2017). "In order to investigate the feasibility of an additional animal model to improve our understanding of EZH2, we collected and investigated naturally occurring canine mammary tumors (CMTs)." (PMID 27502594, 2016). "Growing evidences have established that several essential genes are targeted by EZH2, ultimately leading to tumor growth or metastasis in several carcinomas especially in breast cancer and prostate cancer." (PMID 27835578, 2016). "These analyses are relevant to our work because miR-125b-1 is an EZH2 target in the luminal breast cancer cell line MCF7." (PMID 27386402, 2016). "The discovery of genetic alterations in HMTs that support the importance of epigenetic deregulation in breast cancer has undoubtedly made HMTs, including EZH2, the focus of much attention." (PMID 26868841, 2016). "For example, the first discovery of this regulation is through AKT1 phosphorylation, in which EZH2 is phosphorylated at Ser21 which subsequently alters its affinity for histone H3 in breast cancer." (PMID 27494834, 2016).
breast cancer (continued). "Expression of EZH2 is required for maintenance of a stem cell state in different cancers, including prostate cancer, breast cancer, and glioblastoma." (PMID 27223261, 2016). "We found that inhibition of EZH2 by ZLD1039 in breast cancer cells upregulated several cancer suppressor genes and decreased cell proliferation and cell cycle arrest, as well as induced apoptosis." (PMID 26868841, 2016). "Furthermore, it has been well confirmed that EZH2 is extensively overexpressed and is associated with more aggressive behavior and poor prognosis in a wide range of cancer types, including prostate cancer, breast cancer, melanoma, and non-small cell lung carcinoma." (PMID 27223261, 2016). "Consistent with ours, one study reported that mitogen-activated protein kinase (MAPK) pathway, such as SAPK/JNK, mediated the down-regulation of EZH2, thereby suppressing growth of breast cancer cells by curcumin." (PMID 27421653, 2016). "It has been documented by several research groups that EZH2 is overexpressed in different cancers, and found to repress abnormally different microRNAs, including the miR-181c in prostate and breast cancer cells." (PMID 26983574, 2016). "As we previously reported, curcumin causes G1 arrest of the cell cycle and downregulates the expression of EZH2 through the mitogen-activated protein kinase pathway in breast cancer." (PMID 27049834, 2016). "In breast cancer, EZH2 inhibited the tumor suppressor RKIP transcription through repression-associated histone modifications, therefore promoting tumor progression and metastasis." (PMID 26683709, 2016). "Investigation of the expression of EZH2 in canine mammary tumors revealed that EZH2 protein was overexpressed in canine mammary carcinomas, as in human breast cancer." (PMID 27502594, 2016). "Activation of MEK-ERK signaling pathway has also been associated with EZH2 upregulation in triple negative and ERBB2 positive breast cancer." (PMID 27793053, 2016). "Our study indicated that GSK3β phosphorylates EZH2 at Ser363 and Thr367, resulting in reduced H3K27 trimethylation and biological activity of EZH2 in breast cancer." (PMID 27494834, 2016). "Together with previously published reports, our results further strengthened the role of GSK3β as a tumor suppressor in breast cancer and implied that inactivation of GSK3β is one of the mechanisms enhancing EZH2 activity in cancer." (PMID 27494834, 2016). "This would also be part of reason that high EZH2 expression was correlated with poor OS in breast cancer." (PMID 26683709, 2016). "Both siRNAs substantially reduced the viability of both cell lines, suggesting that the proliferation of breast cancer cells is dependent on EZH2." (PMID 26868841, 2016). "To understand the role of EZH2 in the inhibition of the proliferation of breast cancer cells, we first performed a cell-cycle analysis." (PMID 26868841, 2016). "Thirdly, although pharmacological EZH2 inhibition by DZNep shows broad anti-tumor effect in several cancers, including but not limited to prostate cancer, breast cancer, acute myeloid leukemia, and particular renal cell carcinoma." (PMID 27784285, 2016). "Many cancer cell types exhibit aberrant EZH2 expression, and EZH2 expression is highly correlated with tumor invasiveness in breast cancer." (PMID 26848980, 2016). "In ER-positive breast cancer cells, EZH2 interacts with β-catenin and ER, and functionally enhances gens expression which is independent of PRC2." (PMID 27835578, 2016). "The methylation of H3K27 is catalyzed by the polycomb repressive complex 2 (PRC2) member enhancer of zeste homolog 2 (EZH2/KMT6A), which has been associated with repression of estrogen-responsive genes and with the severity and progression of breast cancer." (PMID 27764788, 2016). "In prostate cancer and breast cancer, EZH2 has been shown to repress the expression of E-cadherin and RUNX3, resulted in promotion of EMT and invasive phenotype and increased cell proliferation, respectively." (PMID 27835578, 2016).
breast cancer (continued). "Similar findings were also observed in other tumors such as breast cancer, bladder cancer, melanoma, as high level of EZH2 were shown to correlate with aggressiveness and advanced disease in each of these cancer types." (PMID 27835578, 2016). "Previously it was shown that RelB and EZH2 are important for the self-renewal of breast cancer TICs." (PMID 27764181, 2016). "In subgroup analysis, the rates of high EZH2 expression in breast cancer, lung cancer and CRC were 0.53 (95%CI: 0.44-0.62), 0.52 (95%CI: 0.42-0.62) and 0.55 (95%CI: 0.29-0.82), respectively." (PMID 26683709, 2016). "In order to determine if these effects are unique to the triple negative subtype of breast cancer, the contribution of RelB and EZH2 to the self-renewal capacity of several ER+ cell lines was tested." (PMID 27764181, 2016). "Further, EZH2 KD was shown to induce a G2/M arrest in breast cancer and regulated cyclin D1, and β-catenin." (PMID 27092879, 2016). "This leads to a possibility of CMT usage as a model for future EZH2 research and clinical trials on breast cancer." (PMID 27502594, 2016). "This suggests a possible role for EZH2 in promoting breast cancer stem cells through the methylation and activation of STAT3." (PMID 27764181, 2016). "Collectively, we showed that H19 was an important factor contributing to drug resistance in breast cancer, and that epigenetic regulation mediated by H19 and EZH2 participates in the acquisition of chemoresistance." (PMID 27845892, 2016). "Knockdown of EZH2 by siRNA has been demonstrated to inhibit breast cancer cell proliferation, whereas pharmacological inhibition of EZH2 results in the apoptosis of breast cancer cells, but not normal cells." (PMID 27938379, 2016). "In a study using the EZH2 inhibitor 3-deazaneplanocin A (DZNep), it was found that its treatment depleted breast carcinoma cells of the PRC2 complex members (EZH2, SUZ12, and EED),and subsequently reactivated expression of IGFBP-3." (PMID 28042859, 2016). "The genetic deletion of EZH2 results in the down-regulation of cyclin D1 in breast cancer and in the up-regulation of p21 in ovarian cancer, causing cell cycle arrest at the G1/S phase." (PMID 26452129, 2015). "Elevated expression of EZH2 has been described in a broad range of cancer types, such as prostate cancer, lung cancer, breast cancer, liver cancer and colon cancer, and has been correlated with aggressive clinical manifestations." (PMID 26452129, 2015). "The inhibition of breast cancer cells growth was observed by dietary omega-3 fatty acids treatment and was related to the downmodulation of EZH2." (PMID 26339624, 2015). "Since Ezh2 is dispensable for mouse prostate and mammary cancer development, we wondered why the enzyme is nonetheless highly up-regulated in tumors." (PMID 26637281, 2015). "In light of these findings, collectively, our results lead us to propose a mechanistic model in which BRCA1 can promote FOXA1 transcriptional expression and thereby, breast cancer luminal subtype development through targeting EZH2." (PMID 25531315, 2015). "To further confirm this finding, we used siRNA to deplete EZH2 in the human breast cancer MCF-7 cells." (PMID 25531315, 2015). "Transgenic EZH2 promotes mammary tumor initiation of tumor virus-neu mice, through increasing the CSC population." (PMID 26484567, 2015). "For instance in breast cancer cells, EZH2 can activate the transcription of different genes in two different manners, depending on the presence or absence of estrogen receptors (ERα)." (PMID 26580594, 2015). "EZH2, a histone 3 lysine 27 (H3K27) methyltransferase, is also significantly overexpressed in breast cancers, and elevated expression of EZH2 protein has been associated with poor prognoses for inflammatory basal-like breast cancers." (PMID 25537518, 2015).